NLRP3 (NLR family pyrin domain containing 3)
Diseases named in the same sentence as NLRP3 in open-access papers (continued):
Sharing a sentence is not in itself a finding about the gene and the disease.
viral infection (continued). "These suggest that the production of NLRP3 inflammasome and its downstream effectors, caspase-1 and IL-1β, is positively correlated with the duration of viral infection." (PMID 40284982, 2025). "The NLRP3 inflammasome can be activated by various viral infections, including SARS-CoV-2, influenza virus, and respiratory syncytial virus." (PMID 39976465, 2025). "Viral infection of M1 macrophages upregulated the mRNA levels of NLRP3, caspase-1, and Gasdermin D (GSDMD)." (PMID 41305513, 2025). "It exhibits unique features that have evolved to adapt to virus infections, such as lower NLRP3 production, greater expression of IFNα1, and greater phosphorylation of IRF3." (PMID 40108733, 2025). "The pathological relevance of NLRP3 is also highlighted by its role in viral infections, where it mediates both antiviral responses and inflammation." (PMID 40851698, 2025). "While activation can assist in controlling viral replication, dysregulated NLRP3 activity contributes to severe pathological outcomes during viral infections." (PMID 40851698, 2025). "In the initial signaling phase, bacterial toxins, viral infections or inflammatory factors trigger NF-κB pathway, leading to upregulation of NLRP3 transcription and synthesis of its precursor proteins." (PMID 40535567, 2025). "Transmissible gastroenteritis virus (TGEV) infection resulted in NLRP3-dependent pyroptosis in porcine intestinal epithelial cells, indicating viral infection promoted host immune responses along with pyroptosis." (PMID 40534781, 2025). "Previous studies have reported that the NLRP3 inflammasome is activated by viral infections or their proteins (15, –, 19)." (PMID 39976465, 2025). "Remarkably, the NLRP3 inflammasome inhibitor MCC950 significantly reduced caspase-1 activity, aligning with previous studies that have demonstrated a central role for NLRP3 in inflammasome activation during viral infections." (PMID 40284946, 2025). "NLRP3 inflammasome is essential for host immune defense against bacterial, fungal, and viral infections." (PMID 40642003, 2025). "In viral infection, PAMPs initiate the activation of the NLRP3 inflammasome, which is composed of NLRP3, ASC, and pro-Caspase-1." (PMID 38643118, 2024). "NLR family pyrin domain containing 3 (NLRP3) is also an important sensor for recognizing cellular stresses, as well as bacterial or viral infections." (PMID 39583041, 2024). "During viral infection, a complex cascade involving NLRP3, ASC and Pro-caspase-1 forms to process the precursors of IL-1β and IL-18 into active forms." (PMID 39038050, 2024). "As a key molecular mechanism in immune regulation, the NLRP3 inflammasome plays an important role in disease development and virus infection." (PMID 38399989, 2024). "Nonetheless, how NLRP12 senses viral infection and interacts with NLRP3 to trigger the assembly of the NLRP12 PANoptosome needs to be clarified first." (PMID 38932258, 2024). "Confirming the intricate involvement of NLRP3 in viral infections, particularly SARS-CoV-2, is pivotal for designing targeted therapeutic approaches." (PMID 38399989, 2024). "The role of NLRP3 in recognizing and responding to viral infections, intracellular bacteria, and protozoans has been largely explored, whereas a few studies have revealed the contribution of NLRP3 in helminth-induced infections." (PMID 38842647, 2024). "During viral infections, RNase L has been demonstrated to promote NLRP3 inflammasome activation through a signaling pathway involving DHX33 and MAVS, leading to the production of IL-1B in bone marrow-derived dendritic cells." (PMID 38473966, 2024). "It is noteworthy that while the involvement of the NLRP3 pathway in viral infections has been preliminarily substantiated, its intricate regulatory mechanisms necessitate further exploration." (PMID 38399989, 2024). "NLRP3 assumes a critical role in immune modulation, rendering it a significant area of exploration within the realm of viral infections." (PMID 38399989, 2024).
viral infection (continued). "In this study, we revealed that PRV VP22, a viral virulence factor, interacted with ZBP1 and suppressed ZBP1-mediated activation of the NLRP3 inflammasome, thereby facilitating viral infection." (PMID 39475237, 2024). "The interaction between Z-DNA binding protein 1 (ZBP1) and the NLR family pyrin domain-containing 3 (NLRP3) inflammasome has been uncovered in several viral infections." (PMID 39475237, 2024). "Here, we identified a novel mechanism that induces ox-mtDNA release to activate the NLRP3 inflammasome during virus infection." (PMID 39213434, 2024). "The activation of the NLRP3 inflammasome is involved in the pathogenesis of diverse viral infections." (PMID 38932258, 2024). "The activation of the NLRP3 inflammasome is closely related to the pyroptosis process induced by viral infections." (PMID 39273156, 2024). "In this study, we reported that the heightened ROS induced by viral infection activates the NLRP3 inflammasome, leading to GSDMD activation." (PMID 38247540, 2024). "Mitochondrial DNA released due to viral infection is detected by receptors (TLR-9, NOD-Like Receptor Thermal Protein Domain Associated Protein 3 (NLRP3), and cyclic GMP-AMP synthase (cGAS)) that typically identify viral or bacterial DNA." (PMID 39742024, 2024). "During viral infection, cardiolipin exposure to the OMM was associated with enhanced NLRP3 and caspase-1." (PMID 39273156, 2024). "Emerging evidence suggests that ZBP1 activates the NLRP3 inflammasome during certain viral infections, leading to IL-1β production and inflammation (23, –, 25)." (PMID 39475237, 2024). "HCV RNA stimulates TLR7 in endosome and primes the transcription of NLRP3 genes and HCV core protein and viral infection-caused K+ efflux triggers the activation of NLRP3 inflammasome." (PMID 38817443, 2024). "Primarily, it impedes the initiation of inflammasomes in both bone marrow-derived macrophages (BMDM) and human pluripotent stem cell-derived macrophages, thereby diminishing the early-stage activation of NLRP3 inflammasomes during viral infection." (PMID 38399989, 2024). "ERK and NF-κB inhibitors also play vital roles in regulating the NLRP3 inflammasome during virus infection." (PMID 38249297, 2023). "Although NLRP3 inflammasome activation and the subsequent inflammation play significant roles in defending against viral infections, SARS-CoV-2 N protein-induced NLRP3 inflammasome activation in innate cells is known to cause hyperinflammation." (PMID 37799713, 2023). "In summary, we can use various approaches to inhibit the activation of the NLRP3 inflammasome during virus infections." (PMID 38249297, 2023). "Multiple endogenous and exogenous stimuli, including virus infections, LPS, and crystalline deposits, can activate the NLRP3 inflammasome." (PMID 36680196, 2023). "To date, several NLRP3 protein inhibitors have been reported to restrain inflammatory effects in viral infection." (PMID 37465759, 2023). "It has been demonstrated that NLRP3 inflammasome can play a crucial role in viral infection pathogenesis." (PMID 37723427, 2023). "NLRP3 is the most extensively studied inflammasome in various viral infections, and is also a major focus of the follow-up discussion in this review." (PMID 37465759, 2023). "Overall, these results indicate that ZBP1 is an essential regulator of the NLRP3 inflammasome in response to viral infection." (PMID 37261341, 2023). "On the other hand, caffeic acid phenethyl ester is an NF-κB inhibitor that regulates the NLRP3 inflammasome after virus infection." (PMID 38249297, 2023). "Activation of the NLRP3 inflammasome through K+ efflux following viral infection: Under normal circumstances, the concentration of potassium ions inside and outside the cells remains balanced." (PMID 37892135, 2023). "Currently, some compounds have been found to have the function of inhibiting the inflammasome (mostly NLRP3), which provides a clear target and idea to inhibit inflammation triggered by viral infection." (PMID 37608944, 2023).
viral infection (continued). "Targeting the activation of inflammasomes, such as the NLRP3 inflammasome, has proven to be a therapeutic target for the control of viral infection due to its exclusive assembly and activation upon viral infection." (PMID 37515138, 2023). "NLRP3 can sense a series of stimuli from viral infection, lysosomal damage, metabolism dysfunction and extracellular ATP." (PMID 36803990, 2023). "Viral infection can stimulate NLRP3 inflammasome activity, thereby aggravating immunological responses that decrease upon aging." (PMID 36680196, 2023). "Some studies have reported that MAVS mediates NF-κB and type I interferon signaling during viral infection and is also required for optimal NLRP3 inflammasome activity." (PMID 37901251, 2023). "During virus invasion, the excessive activation of the NLRP3 inflammasome can lead to a cytokine storm that increases virus infection and damages the tissues." (PMID 38249297, 2023). "ROS plays a pivotal role as a regulator of NLRP3 inflammasome activation induced by viral infections." (PMID 37892135, 2023). "We also discuss several therapeutic strategies targeting the NLRP3 inflammasome for anti-inflammatory effects in virus infection." (PMID 38249297, 2023). "Activation of the NLRP3 inflammasome occurs following viral infections by mobilizing Ca2+: The core protein of the HCV is capable of mobilizing intracellular Ca2+ through a mechanism associated with phospholipase-C activation." (PMID 37892135, 2023). "The NLRP3 inflammasome is known as a critical component of the innate immune system against various viral infections, including enteroviral infections, and mitochondria play an important role in NLRP3 activation." (PMID 36851568, 2023). "Aberrant NLRP3 activation is central to deleterious inflammation in severe viral infections, nervous system diseases, metabolic diseases, autoimmune diseases, and cancer." (PMID 37651190, 2023). "An increasing number of studies have reported a relationship between viral infection and NLRP3 inflammasome activation." (PMID 37243164, 2023). "The nucleotide-binding oligomerization domain (NOD)-like receptor protein 3 (NLRP3) inflammasome plays a vital role in innate immune responses and has garnered considerable attention in the context of virus infection." (PMID 38249297, 2023). "Viral infections activate the NLRP3 inflammasome and inhibit its assembly and activation through interactions." (PMID 37892135, 2023). "Following initiation, NLRP3 is activated in response to bacterial, fungal, and viral infections and DAMPs-mediated sterile inflammation." (PMID 37892135, 2023). "There is a complex relationship between viral infection and the nucleotide-binding oligomerization domain-like receptors family pyrin domain-containing 3 (NLRP3) inflammasome." (PMID 37243164, 2023). "Among the many pathways involved, the nucleotide-binding oligomerization domain (NOD)-like receptor protein 3 (NLRP3) inflammasome has received wide attention in the context of viral infection." (PMID 38249297, 2023). "Normally, activation of the nucleotide-binding oligomeric domain-like receptor containing pyrin domain 3 (NLRP3) inflammatory vesicles induces cytokine production as an inflammatory response to viral infection." (PMID 37868953, 2023). "The RIP1-RIP3-DRP1 pathway is a common route for activating the NLRP3 inflammasome during viral infections." (PMID 37892135, 2023). "have reported that MAVS mediates NF-κB and type I interferon signaling during viral infection and is also required to activate the NLR family pyrin domain containing 3 (NLRP3) that triggers an immune response.." (PMID 38187378, 2023). "MAVS also physically interacts with the NLRP3, and it has been suggested that MAVS is required for the NLRP3 inflammasome activation by viral infections." (PMID 37692170, 2023). "The activation of microglial NLRP3 inflammasome in the brain has also been demonstrated after viral infection with JEV and WNV." (PMID 36316366, 2023).
viral infection (continued). "Recently, the interaction between ZBP1 and NLRP3 inflammasome has been revealed in several viral infections." (PMID 37261341, 2023). "Viral infections can induce an imbalance in intracellular ion concentrations, leading to mitochondrial damage and lysosome rupture, activating the NLRP3 inflammasome." (PMID 37892135, 2023). "The results illustrate the mechanism by which type I IFNs responses control inflammasome activation and viral infection–induced aberrant NLRP3 activation." (PMID 37651190, 2023). "The authors showed that host IL-1β increases in infected animals with both IL-1β and NLRP3 acting as restriction factors to control viral infection in the CNS." (PMID 36298668, 2022). "The present study provides new insights to the inflammatory injuries induced by FAdV-4 infection and is significant for the future investigation on the NLRP3 inflammasome activation mechanism against viral infection." (PMID 35077922, 2022). "Activation of NLRP3 inflammasome and upregulation of the secretion of IL-1β in mice and human macrophages by viral infection have been proved previously." (PMID 35077922, 2022). "As expected, after viral infection, the amount of mature IL-1β released from samples expressing NLRP3-GFP was similar to that in cells expressing either NLRP3 or Flag-NLRP3." (PMID 35062292, 2022). "The data thus revealed the enhanced activation of NLRP3 inflammasome in senescent macrophages upon viral infection." (PMID 35313074, 2022). "This review illustrates that two main inflammasome sensors have been well studied in the context of viral infection: NLRP3 and AIM2." (PMID 36298668, 2022). "Specifically, the NLRP3 inflammasome is known to activate following viral infection and respond to a variety of stimuli including sensing changes in cytosolic ion concentrations." (PMID 36580480, 2022). "The involvement of the CLEC5A signaling in the activation of NLRP3 inflammasome and resulting IL-1b production have been already described during viral infections with DV and JEV as well as in the infection with L. monocytogenes." (PMID 35252461, 2022). "Over and above established microbial settings, NLRP3 contributes to immunopathology and innate and adaptive immunity quality during viral infection." (PMID 35806033, 2022). "This correlated with increased viral titer and significant lung damage suggesting NLRP3 inflammasome activation is critical to reduce respiratory viral infection-induced morbidity and mortality." (PMID 36580480, 2022). "This brief review will focus on the recent research advances of NLRP3 inflammasome activation in response to viral infection throughout the development and progression of IPF." (PMID 34638790, 2021). "There is growing evidence that inflammasome structures like AIM2 and especially NLRP3 are involved in triggering inflammatory response during virus infection including that of SARS-CoV-2." (PMID 34960782, 2021). "Although type I IFNs, SGs, and the NLRP3 inflammasome are required for host defense responses during viral infections, the mechanisms regulating coordination of these responses to ultimately exert protection during IAV infection are not clear." (PMID 33766561, 2021). "In fact, it has been reported that DRP1-mediated mitochondrial fission leads to the activation of the NLRP3 inflammasome upon viral infection, and NLRP3 inflammasome activation is augmented by DRP1 knockdown." (PMID 33670748, 2021). "As components of the inflammasomes, NOD-like receptor pyrin domain containing 1 and 3 (NLRP1 and NLRP3) are important in mediating host immune response against viral infections by initiating inflammation." (PMID 33918087, 2021). "Inhibition of NLRP3 activation can be either protective or detrimental depending on the stage of viral infection." (PMID 33652815, 2021).
viral infection (continued). "Viral infection activates the NLRP3 inflammasome via viral proteins, endoplasmic reticulum (ER) stress, mitochondria dysfunction, ROS production, protein aggregates, and aberrant ion concentrations." (PMID 34638790, 2021). "Based on the regulation of NLRP3 inflammasome by ncRNAs, novel therapeutic strategies against viral infections are in development." (PMID 34944639, 2021). "The viral infection initiates the intracellular nuclear factor kappa-light-chain enhancer of the activated B cells (NF-κB) signalling pathway, which contributes to NLRP3, IL-1B, and IL-18 expressions." (PMID 34360684, 2021). "Overall, viral infection triggers ER stress- and NLRP3 inflammasome-induced inflammation signaling cascades via complex mechanisms that involve cell stressors, such as mitochondrial stress, cytokines, RIP1, and Angiotensin II." (PMID 34638790, 2021). "Viral infection-triggered NLRP3 inflammasomes play vital roles in the development of organ fibrosis." (PMID 34638790, 2021). "In COVID-19 pneumonia, the occurrence of fatal NLRP3 inflammasome aggregates in the lungs indicated a possible molecular interaction between viral infection and cytokine storm formation." (PMID 34944639, 2021). "Predominantly, the NLRP3 inflammasome has been reported to enhance antiviral immune responses against virus infection." (PMID 34065500, 2021). "In particular, upon viral infection, ALR or NLR families, including NLRP1, NLRP2, NLRP3, and AIM2, detect pathogen-associated molecular patterns (PAMPs) and assemble an intracellular inflammasome complex by recruiting ASC and pro-caspase-1." (PMID 34360684, 2021). "The physical interaction between MAVS and NLRP3 is required for NLRP3 inflammasome activation during viral infection." (PMID 34336092, 2021). "All this evidence supports mitochondria as central regulators of NLRP3 inflammasome activation induced by ER stress, virus infections and the NLRP3 activators accompanying mitochondrial dysfunction to promote the activation of NLRP3 inflammasome." (PMID 34638790, 2021). "MFN2 appears to be a key regulator of innate immunity, as it interacts with MAVS, NLRP3, and various other signaling molecules during viral infections." (PMID 34482801, 2021). "Among the viral proteins, viroporins are present in both DNA and RNA viruses involved in different stages of the virus infection cycle and can induce NLRP3 inflammasome activity." (PMID 34638790, 2021). "During influenza virus infection, NLR family members are known to play important roles to regulate antiviral responses, especially for NLRP3 inflammasome since it has been reported to mediate several virus infections via promoting antiviral immune responses." (PMID 34065500, 2021). "NLRP3 is activated by sensor proteins during viral infections once PAMPs are detected by cell surface receptors such as TLR2/4 and TREM family receptors." (PMID 33923537, 2021). "NLRP3 inflammasome activation is also critical for host defense and pathogen elimination in fungal, bacterial, and viral infections." (PMID 33936034, 2021). "NLRP3 plays a critical role for host immune defences against bacterial, fungal, and viral infections." (PMID 33794925, 2021). "NLRP3 and MyD88 are primary activators of cytokine storm in human cells in response to pro-inflammatory stimuli, as well as bacterial and viral infection." (PMID 33096896, 2020). "Among all the known inflammasomes, the NLRP3 inflammasome is the most significantly studied in viral infections and suggested to play a decisive role in both inflammation and antiviral responses." (PMID 33014899, 2020). "Although a variety of pathogen senses the PAMP and DAMPs and activate diverse inflammasomes, study shows a range of virus infection that activates inflammasomes such as the NLRP3, AIM2, and RIG-I and mediate the robust host immune response." (PMID 33014899, 2020).